FTO (FTO alpha-ketoglutarate dependent dioxygenase)
Diseases named in the same sentence as FTO in open-access papers (continued):
Sharing a sentence is not in itself a finding about the gene and the disease.
glioma (continued). "Predicted miR-27a-3p binding and regulation of FTO were verified, and the dynamic effects of the miR-27a-3p/FTO axis on hypoxia-challenged glioma cells were investigated." (PMID 36718644, 2023). "In FTO-overexpressing glioma cells exposed to hypoxia, the percentage of cells with m6A RNA methylation was significantly decreased; in contrast, under normoxia, FTO knockdown significantly increased the percentage of m6A RNA-methylated cells." (PMID 36718644, 2023). "We found that several SNPs were associated with the increased risk of glioma, including the WTAP rs7766006, YTHDF2 rs3738067, and FTO rs9939609 polymorphisms." (PMID 36733406, 2023). "More importantly, FTO has been reported to serve as a tumor suppressor in gliomas by interacting with FOXO3a, enhancing FOXO3a nuclear translocation and target gene expression." (PMID 36718644, 2023). "Conclusively, FTO serves as a tumor suppressor in glioma by suppressing hypoxia-induced malignant behaviors of glioma cells, possibly by promoting the nuclear translocation of FOXO3a and upregulating FOXO3a downstream targets." (PMID 36718644, 2023). "Consistently, we also observed downregulated mRNA expression and decreased protein levels of FTO in glioma intermediate and core regions, as well as hypoxia-challenged glioma cells." (PMID 36718644, 2023). "Taoet al. reported that FTO protein contents were downregulated in gliomas compared with normal tissue samples." (PMID 36718644, 2023). "Conclusively, FTO serves as a tumor suppressor in glioma by suppressing hypoxia-induced malignant behaviors of glioma cells." (PMID 36718644, 2023). "miR-27a-3p directly binds to FTO to dramatically inhibit its expression in hypoxia-challenged glioma cells." (PMID 36718644, 2023). "In this study, in contrast to FTO, miR-27a-3p expression was upregulated in the intermediate and core regions of gliomas, as well as in hypoxia-challenged glioma cells." (PMID 36718644, 2023). "miR-27a-3p overexpression promotes hypoxia-challenged glioma cell aggressiveness, whereas FTO overexpression partially diminishes the oncogenic effects of miR-27a-3p overexpression." (PMID 36718644, 2023). "Knockdown of FTO in human glioma cell lines or via treatment with a selective inhibitor of FTO was thought to inhibit cell proliferation and migration." (PMID 35625706, 2022). "In summary, these data indicated that FTO regulated the feedback loop in glioma cells by targeting MYC transcripts." (PMID 35625706, 2022). "JPX (lncRNA proximal inactive specific transcript) mediates PDK1 mRNA demethylation in glioma drug resistance by combining with the m6A demethylase FTO." (PMID 36437944, 2022). "Li’s group reported that FTO expression in glioblastoma was lower than in low-grade glioma and normal brain tissue." (PMID 35625706, 2022). "In glioma, studies found the m6A-SNPs, rs7766006 (WTAP), rs3738067 (YTHDF2), and rs9939609 (FTO), to increase cancer risk, whereas rs2293595 (YTHDC1), rs3813832 (YTHDC1), and rs8047395 (FTO) reduced the risk." (PMID 34151731, 2021). "Studies have shown that as the WHO grade is increased, the expression of WTAP, RBM15, YTHDF, and ALBKH5 is increased, while the expression of FTO is decreased in glioma." (PMID 33718165, 2021). "The reader YTHDF2 and the eraser FTO promotes cancer cell proliferation in pancreatic cancer and glioma." (PMID 32850303, 2020). "Generally, the high expression of m6A regulators indicated a higher grade of glioma; whereas the high expression of FTO indicated a lower grade of glioma." (PMID 33240891, 2020). "FTO plays carcinogenic roles through maintaining the stability of gliomas, especially the stability of oncogene homologues (c-Myc) and CCAAT-enhancer-binding protein-α (CEBPA) transcripts in IDH1/2 mutant gliomas." (PMID 32943100, 2020). "In turn, this should mean that, in glioma just as in leukemia, tumours with high FTO levels and low/medium MYC levels should be the most sensitive ones to R-2HG treatment." (PMID 32316617, 2020).
glioma (continued). "Of course, a corollary of their observation should be that, in low grade, IDH1/2 mutant gliomas, the levels of FTO, kept low by R-2HG, result in an overall high level of m6A (or likely m6Am) RNA methylation, particularly relevant on MYC transcripts." (PMID 32316617, 2020). "Although FTO is upregulated in gliomas, it may counteract abnormal methylation, serving as a compensatory mechanism that reduces the malignancy of gliomas." (PMID 40469294, 2025). "For m6A erasers, the expression of FTO is generally lower in glioma tissues than in normal tissues." (PMID 40469294, 2025). "Thus, increased expression of ALKBH5 and decreased expression of FTO can be used to predict the poor prognosis of gliomas." (PMID 40469294, 2025). "Another m6A eraser, FTO, has been shown to promote glioma onset by targeting MYC mRNA." (PMID 40469294, 2025). "Artificially blocking the high expression of FTO via the application of miR-27a-3p could significantly promote the progression of glioma." (PMID 40469294, 2025). "While tumor suppressive functions for FTO have been described in for example colorectal cancer and hepatocellular carcinoma, reports describing oncogenic functions in different cancer types including lung cancer, glioma and AML are far more abundant." (PMID 40022434, 2025). "Furthermore, reports indicate that FTO can inhibit glioma growth and invasion, making it a potential suppressor of GBM." (PMID 40469294, 2025). "For instance, therapies like EREG monoclonal antibodies or selective PI3K/Akt inhibitors, many of which are in clinical development, could be repurposed for glioma subtypes characterized by low FTO expression." (PMID 40970086, 2025). "Given the consistent clinical observation of reduced FTO expression in high-grade gliomas, we hypothesized that FTO functions as a tumor suppressor." (PMID 40970086, 2025). "Interestingly, inhibition of FTO led to the growth characteristics of wildtype IDH gliomas to be more consistent with IDH mutant growth phenotype." (PMID 39596840, 2024). "Recent studies also posit that D-2-HG treatment can inhibit glioma cell viability in a dose-dependent fashion (Su and colleagues, 2018) and that D-2-HG can inhibit FTO in IDH1mut acute myeloid leukemia cells to increase m6A abundance and slow cell proliferation." (PMID 38445960, 2024). "FTO inhibition represents a potential therapeutic target for IDH1wt gliomas and possibly in conjunction with IDH1mut inhibitors for the treatment of IDH1mut glioma." (PMID 38445960, 2024). "Coupled with the higher affinity of D-2-HG for FTO versus ALKBH5 at the molecular level, our experiments indicate that IDH1mut-generated D-2-HG inhibits FTO to induce m6A hypermethylation that ultimately results in the slower growth phenotype seen in IDH1mut gliomas." (PMID 38445960, 2024). "The knockdown and overexpression results indicate that FTO may play a more important role in regulating glioma cell proliferation." (PMID 38445960, 2024). "The metabolic function of FTO may differ across glioma developmental stages or tissue subtypes, potentially exerting contrasting effects." (PMID 37964279, 2023). "Although the roles of FTO and miR-27a in glioma have been widely recognized, their functions in a hypoxic microenvironment remain unclear." (PMID 36718644, 2023). "Furthermore, FTO overexpression partially abolished the effects of miR-27a-3p on hypoxia-challenged glioma cells, suggesting that FTO is downstream of miR-27a-3p, eliminating the oncogenic effects of miR-27a-3p." (PMID 36718644, 2023). "miR-27a-3p is a major contributor to FTO downregulation in glioma under hypoxia." (PMID 36718644, 2023). "However, FTO expression is downregulated in glioma, particularly in the core and intermediate regions; therefore it is necessary to investigate the contributor(s) to FTO downregulation." (PMID 36718644, 2023). "MA, as an FTO inhibitor with high selectivity, offers a novel approach to glioma drug research." (PMID 38072944, 2023).
glioma (continued). "Nevertheless, FTO expression levels are positively related to the increasing malignancy of gliomas." (PMID 38072944, 2023). "The aberrant expression levels of FTO suggest its potential role in glioma adaptation to hypoxia." (PMID 36718644, 2023). "Developing more selective inhibitors of FTO and other m6A regulatory factors may help develop effective treatments for life-threatening gliomas." (PMID 38072944, 2023). "Under normoxia, FTO knockdown enhanced the viability, migration, and invasion of glioma cells." (PMID 36718644, 2023). "miRNAs that were differentially expressed in hypoxia-challenged glioma cells and might target FTO were analyzed and miR-27a-3p was selected." (PMID 36718644, 2023). "Consistently, under hypoxia, lv-FTO transduction suppressed glioma cell viability, cell migration, and cell invasion, whereas agomir-27a-3p exerted opposite effects on glioma cell phenotypes; similarly, the oncogenic effects of agomir-27a-3p on glioma cells were partially diminished by lv-FTO." (PMID 36718644, 2023). "Considering these previous findings, FTO might exert its role in glioma by interacting with FOXO3a and modulating FOXO3a target gene expression." (PMID 36718644, 2023). "Inhibiting the expression of FTO enhances the effect of temozolomide on glioma." (PMID 34212046, 2021). "Whether ALKBH5 plays a preferential role than FTO in glioma or whether they are specific for modification sites is worth further study." (PMID 33264518, 2021). "The “eraser” FTO is also a particularly promising therapeutic target for glioma and other cancers." (PMID 32296573, 2020). "As is visible in the violin plot, the mRNA expression levels of YTHDF2, YTHDF1, METTL3, RBM15 and HNRNPC were up‐regulated in glioma compared to normal tissues, whereas the expression levels of ALKBH5, WTAP, YTHDC2, ZC3H13 and METTL14, especially of FTO, were decreased in glioma." (PMID 32449290, 2020). "Moreover, the expressions of WTAP, RBM15, YTHDF2, YTHDF1 and ALKBH5 were highly correlated with each other, and all of their expressions were negatively correlated with FTO in gliomas." (PMID 30810537, 2019). "Interestingly, the expression of FTO was significantly deceased in gliomas with malignant clinicopathological features, such as higher WHO grade, mesenchymal subtype, IDH-wildtype status, 1p/19q noncodel and older ages at diagnosis." (PMID 30810537, 2019). "Therefore, FTO is generally considered a protective factor against glioma progression." (PMID 40469294, 2025). "The integration of FTO expression into multivariable prognostic models, alongside established markers like IDH status and MGMT promoter methylation, could potentially enhance risk stratification and guide personalized treatment decisions for glioma patients." (PMID 40970086, 2025). "Having established the predominant role of FTO inhibition versus ALKBH5 inhibition in m6A hypermethylation in IDH1wt glioma cells, we employed FTO-specific small-molecule inhibitors, FB23-2 and MA, to test whether pharmacologic FTO inhibition might provide a tractable treatment strategy." (PMID 38445960, 2024). "Thus, under hypoxia, FTO serves as a tumor suppressor in glioma cells." (PMID 36718644, 2023). "The FTO/m6A/MYC/CEBPA signaling pathway may be related to TMZ resistance in glioma cells." (PMID 36437944, 2022). "Meclofenamic acid (MA2) also inhibits the expression of FTO, thus enhancing the ability of the chemotherapy drug TMZ to suppress the proliferation of glioma cells." (PMID 40469294, 2025). "Therefore, inhibiting FTO overexpression may be an effective method for treating glioma." (PMID 40469294, 2025). "Overexpression of FTO effectively suppressed the IGF2BP3-induced upregulation of MIB1 and overall increase in m6A, inhibiting IGF2BP3-induced NETosis and glioma cell survival." (PMID 38167409, 2024).
glioma (continued). "Subsequently, overexpression experiments for METTL3, FTO, and ALKBH5 were conducted in glioma cells." (PMID 38405130, 2024). "In this study, we demonstrate that, in glioma, upregulation of IGF2BP3 enhances the expression of E3 ubiquitin protein ligase MIB1, promoting FTO degradation via the ubiquitin-proteasome pathway." (PMID 38167409, 2024). "Particularly, the erasers FTO and ALKBH5 exhibit a range of activities impacting various aspects of glioma biology." (PMID 38474421, 2024). "In this work, we report that IGF2BP3 initiates a reciprocal regulation between MIB1 and FTO to drive m6A-mediated NET formation and glioma progression." (PMID 38167409, 2024). "The results showed that METTL14, FTO, YTHDF1, and YTHDF3 demonstrated significant upregulation in low-grade gliomas compared to normal tissues." (PMID 38398118, 2024). "Combined treatment with the FTO inhibitor MA2 can improve the inhibitory effect of chemotherapeutic temozolomide (TMZ) on the proliferation and invasion of glioma cells." (PMID 38072944, 2023). "The ethyl ester form of the FTO inhibitor Meclofenaic (MA2) inhibits FTO and enhances the effect of the chemotherapeutic drug temozolom by targeting the MYC-miR-155/23a cluster-MXI1 feedback circuit in gliomas anti-tumor effects." (PMID 35707365, 2022). "It inhibits migration and invasion in pancreatic cancer cells and the eraser FTO is an oncogene in AML and glioma." (PMID 34521394, 2021). "METTL14 has been reported as a tumor suppressor gene in GBM, and the erasers FTO and ALKBH5 are oncogenes in glioma." (PMID 33134160, 2020). "The ethyl ester form of meclofenamic acid (MA2) inhibits FTO and enhances the effect of the chemotherapy drug temozolomide (TMZ) on suppressing proliferation of glioma cells." (PMID 33015074, 2020). "Only text mining evidence supported the interaction of ALKBH5 and FTO in the String database, and the expressions of ALKBH5 and FTO were negatively correlated with each other in gliomas." (PMID 30810537, 2019). "Furthermore, FTO expression was significantly lower in U251 and U87MG glioma cell lines compared to the HMC3 normal microglial cell line." (PMID 40970086, 2025). "Similarly, the downregulated expression of FTO enhances the m6A modification of primary microRNA-10a (pri-miR-10a), which can be recognized by the reader HNRNPA2/B1 and increase the glioma tumour burden." (PMID 40469294, 2025). "The FTO inhibitor R-2-hydroxyglutarate (R-2HG) displays anti-tumor activity in non-IDH mutant AML and glioma by targeting FTO/m6A/MYC/CEBPA signaling." (PMID 40483535, 2025). "Along with increased expression of FTO, the m6A modification level significantly decreases and consequently increases the expression of HSP90, which interferes with the apoptotic system and promotes glioma development." (PMID 40469294, 2025). "Interestingly, in contrast to FTO expression, increased ALKBH5 expression in gliomas implies a poorer prognosis." (PMID 40469294, 2025). "Given the roles of FTO and ALKBH5 in modulating cell death in glioma, focusing on how these m6A erasers influence apoptosis and ferroptosis, especially in GSCs, could be valuable." (PMID 38474421, 2024). "As inferred fromFigure 5C, unlike FTO, higher expression of miR-27a-3p predicted poorer prognosis in glioma patients." (PMID 36718644, 2023). "FTO overexpression enhances the stability of c-MYC mRNA through the m6A methylation-dependent mechanism, thereby improving MYC transcription, promoting the MYC feedback loop, and enhancing malignant characteristics of glioma cells." (PMID 38072944, 2023). "Bioinformatics analysis of the China Glioma Genome Atlas Project (CGGA) microarray and RNA-sequencing database revealed that both m6A writers and readers were significantly increased, while erasers such as FTO were relatively decreased." (PMID 36437944, 2022). "Furthermore, FTO inhibitor and MA2 increased the antitumor effect of temozolomide on decreasing the viability of glioma cells." (PMID 34745970, 2021).
glioma (continued). "In glioma, MA2, which could be an FTO inhibitor, notably inhibited cell proliferation compared with a single treatment group." (PMID 34745970, 2021). "In this study, R-2HG was used to directly inhibiting FTO in AML and glioma cells, which resulted in increased methylation and decreased expression of c-MYC and CEBPA mRNAs, blocking proliferation, cell cycle, and inducing apoptosis in AML and glioma cells." (PMID 33461542, 2021). "In glioma, mutations occur only in 0.1% of cases for m6A ereasers ALKBH5 and no mutations have been reported in FTO." (PMID 33718165, 2021). "Other studies also show that FTO functions as an oncogenic role via maintaining the stability of transcripts of avian myelocytomatosis viral oncogene homolog (c-Myc) and CCAAT enhancer binding protein alpha (CEBPA) in glioma, especially IDH1/2 mutant glioma." (PMID 32244981, 2020). "This also indicates that FTO and ALKBH5 may preferentially mediate demethylation of different methylation targets in glioma, and it is worth investigating in future studies." (PMID 30810537, 2019). "Our findings demonstrate that FTO suppresses glioma proliferation and cell cycle progression by regulating the stability of Epiregulin (EREG) mRNA and subsequently inactivating the PI3K/Akt signaling pathway, thereby establishing its role as a key tumor suppressor in glioma." (PMID 40970086, 2025). "We also show how this IDH1mut → D-2-HG ⊣ FTO axis may inhibit tumor growth through downregulation of activating transcription factor 5 (ATF5) mRNA, a transcription factor involved in proliferation and apoptosis in glioma." (PMID 38445960, 2024). "In exploring downstream effectors of our proposed IDH1mut → D-2-HG ⊣ FTO axis using bioinformatic and biologic experiments, we identified ATF5 (an oncogenic protein involved in proliferation and suppression of apoptosis) as a mediator of glioma growth inhibition." (PMID 38445960, 2024). "Furthermore, METTL3, FTO, and YTHDC1 were higher in IDH-mutant LGG and GBM than in wild-type gliomas; however, this did not mean that the RNA was more or less methylated (more than m6A/m5C) in IDHm gliomas." (PMID 37964279, 2023). "It’s becoming more and more clear that methylation regulators of the area of m6A in RNA, such as FTO and YTHDF2, may have an impact on glioma cell proliferation, carcinogenesis, proliferation and growth and invasion by influencing the levels of mRNA expression in their target genes." (PMID 37733705, 2023). "Studies also have shown that FTO may play an oncogenic role via maintaining the stability of transcripts of avian myelocytomatosis viral oncogene homolog (c-Myc) and CCAAT enhancer binding protein alpha (CEBPA) in glioma, especially IDH1/2 mutant glioma." (PMID 33718165, 2021). "In addition, FTO showed a consistent downregulation at the mRNA level of glioma, GBM, and LGG, but not at the protein level of GBM." (PMID 34589481, 2021). "We performed selective short hairpin RNA (shRNA) knockdown experiments to further assess the possibility that FTO, rather than ALKBH5, is the main mediator of D-2-HG effects on m6A in glioma." (PMID 38445960, 2024).